ADAM29 (ADAM metallopeptidase domain 29)
Description:
May be involved in spermatogenesis and fertilization. Seems to be a non catalytic metalloprotease-like protein.
Synonyms: CT73; svph1
Tractability: Antibody: its Gene Ontology location is reachable by antibodies, with high confidence; UniProt predicts a signal peptide or a membrane-spanning region.
Gene: Protein-coding gene on chromosome 4 (174,829,668 to 174,978,180, forward strand). Ensembl gene ENSG00000168594.
Subcellular location: Membrane
Gene Ontology:
Molecular function: metalloendopeptidase activity; metallopeptidase activity
Biological process: male gonad development; proteolysis; spermatogenesis
Cellular component: external side of plasma membrane; plasma membrane; sperm head plasma membrane; membrane
Genetic constraint (gnomAD): Loss-of-function variants: 4 observed, 2.42 expected, observed/expected ratio (o/e) 1.65, 90% interval 0.68 to 1.94. That is too few expected variants to judge how well the gene tolerates losing a copy. Missense variants: 969 observed, 1,042 expected, observed/expected ratio (o/e) 0.93, 90% interval 0.88 to 0.98. Synonymous variants: 367 observed, 355.32 expected, observed/expected ratio (o/e) 1.03, 90% interval 0.95 to 1.13.
Homologues: Orthologues: chimpanzee ADAM29 (98% identical), macaque ADAM29 (90% identical), pig ADAM29 (56% identical), mouse Adam29 (53% identical), tropical clawed frog XB990656 (27% identical), zebrafish adam9b (26% identical), Caenorhabditis elegans unc-71 (23% identical), Drosophila melanogaster kuz (17% identical), zebrafish adam10a (17% identical), Drosophila melanogaster mmd (17% identical), Caenorhabditis elegans sup-17 (16% identical), zebrafish adam10b (14% identical), and 1 more. Paralogues in human: ADAM20 (45% identical), ADAM21 (43% identical), ADAM9 (31% identical), ADAM30 (31% identical), ADAM19 (27% identical), ADAM12 (26% identical), ADAM32 (24% identical), ADAM22 (24% identical), ADAM8 (24% identical), ADAM18 (24% identical), ADAM2 (23% identical), ADAM28 (23% identical), and 8 more.
Diseases named in the same sentence as ADAM29 in open-access papers:
ADAM29 is named in the same sentence as 14 diseases in open-access papers, as found by Europe PMC text mining. Sharing a sentence is not in itself a finding about the gene and the disease. The quoted sentences say what the papers report.
melanoma (2 papers, 2013 to 2024). A malignant, usually aggressive tumor composed of atypical, neoplastic melanocytes. "The alternative expression levels of these genes in certain organs may act as an indicator of cancer development, including WFDC2 in ovarian cancer, ADAM29 and ADAM7 in melanoma and Eppin in prostate cancer." (PMID 24137416, 2013).
COVID-19 (1 paper, 2022). A disease caused by infection with severe acute respiratory syndrome coronavirus 2. "We found that the expression of the antiviral genes negatively correlated (except ADAM7, ADAM11, ADAM12, ADAM18, ADAM20, and ADAM29) with the HRCT score of the COVID-19 patients suggesting association of increased antiviral response with decreased disease severity." (PMID 36532041, 2022).
gastric cancer (1 paper, 2024). A primary or metastatic malignant neoplasm involving the stomach. "ADAM29 has been demonstrated to promote gastric cancer cell proliferation, migration, and invasion, with increased expression associated with poor patient survival." (PMID 39408230, 2024).
lung carcinoma (1 paper, 2022). "A CTA panel of NY-ESO-1, XAGE-1, ADAM29 and MAGE-C1 had specificity and sensitivity values of 89% and 36%, respectively, in lung cancer patients." (PMID 35574342, 2022).
steatosis (1 paper, 2024). Increased lipid within the cytoplasm of cells. "Although 100% of both Adam29+/+ and Adam29−/− mice presented microvacuolar steatosis, the incidence of macrovacuolar steatosis and hepatocyte hypertrophy was reduced in Adam29−/− animals, whereas inflammation incidence was higher in these animals." (PMID 38966569, 2024).
cancer (5 papers, 2008 to 2024). A tumor composed of atypical neoplastic, often pleomorphic cells that invade other tissues. "Pan-cancer SNV analysis revealed relatively high mutation frequencies in ADAM29, ADAM7, and ADAM18, with mutations predominantly observed in SKCM and UCEC." (PMID 39346916, 2024).
tumor (4 papers, 2015 to 2023). "We found that drinking status was associated with TMB and frequent FAT1 and ADAM29 mutations, implying that lifestyle factors might shape different mutational landscapes and the tumor biology of ESCC." (PMID 34885197, 2021).
ADAM29 also shares sentences with these, for which no sentence is quoted: breast carcinoma (3 papers); focal segmental glomerulosclerosis (1); infertile (1); kidney diseases (1); lupus nephritis (1); ovarian carcinoma (1); prostate carcinoma (1).